NLRP3 (NLR family pyrin domain containing 3)
Diseases named in the same sentence as NLRP3 in open-access papers (continued):
Sharing a sentence is not in itself a finding about the gene and the disease.
gout (continued). "Activation of the NLRP3 inflammasome also plays a crucial role in the acute symptoms of gout, leading to the release of IL-1β and other pro-inflammatory cytokines." (PMID 38468241, 2024). "Collectively, these findings showed that HECTD3 in myeloid cells reduced MSU-induced gouty arthritis, a NLRP3-dependent disease via suppressing the activation of the NLRP3 inflammasome." (PMID 38267403, 2024). "Conclusively, NCOA6 is a critical regulator of NLRP3 inflammasome activation and is therefore a promising target for NLRP3-dependent diseases, including gout." (PMID 38195836, 2024). "We demonstrate that HECTD3 inhibits gouty arthritis, a NLRP3-related inflammatory disease by inhibiting assembly and activation of the NLRP3 inflammasome." (PMID 38267403, 2024). "The target genes of Terpine-4-ol, a main compound of ZP, were overlapped with the gouty arthritis-related genes such as NLRP3, PTGS2, CXCL8, IL6, TNF, IL1B, TLR4, and ALB." (PMID 39861092, 2024). "Gallic acid has been reported to be able to improve ulcerative colitis in mice by suppressing NLRP3 inflammasome and alleviate gouty arthritis by enhancing Nrf2 signaling and repressing NLRP3 inflammasome activation and cleavage." (PMID 39139945, 2024). "Further study found that through MSU injection to replicate the gout rat model, DTX substantially attenuates NLRP3 protein expression and ameliorates gout symptoms." (PMID 39170709, 2024). "For instance, studies have demonstrated the pivotal role of NLRP3 in gout and pseudogout, highlighting the therapeutic potential of targeting inflammasome pathways in inflammatory diseases." (PMID 38919626, 2024). "Research conducted using animal models has demonstrated that ozone therapy significantly alleviated symptoms of acute gouty arthritis by inhibiting the NLRP3 inflammasome, a critical component of the inflammatory response in gout." (PMID 39409183, 2024). "Endogenous stimulatory factors such as MSU crystals can induce the body to produce a large amount of IL-1β and other inflammatory factors by activating the NLRP3 inflammasome signaling pathway, thereby inducing gouty arthritis." (PMID 39544522, 2024). "Recently, it has been recognized that the innate immune system mediated through activation of NLRP3 inflammasome triggered by MSU crystals is involved in the pathogenesis of gouty arthritis." (PMID 39065733, 2024). "The literature has reported that the activation of the NLRP3 inflammasome is a crucial signal transduction pathway for inducing the occurrence and development of gouty arthritis." (PMID 39544522, 2024). "While often considered a lifestyle-related disease, gout exemplifies NLRP3 activation through monosodium urate (MSU) crystal formation due to purine metabolism dysfunction." (PMID 39301197, 2024). "Gout flares, disproportionately frequent at night, appear significantly influenced by circadian rhythm, which regulates NLRP3 inflammasome activation, and phagocyte behaviour, and is subject to altered epigenomic modulation in gout patients." (PMID 38493256, 2024). "We further explored the anti-HUA and anti-gout effects of ER in the in vivo model through the modulation of NLRP3 inflammasome." (PMID 38708084, 2024). "Numerous studies have aimed to find natural remedies that can treat gouty arthritis by regulating IL-1β through targeting the NLRP3 inflammasome." (PMID 39861092, 2024). "Colchicine, a recognized NLRP3 inhibitor traditionally used for gout, has shown the potential to reduce cardiovascular risks in clinical trials, emphasizing NLRP3’s significant role in cardiovascular disease progression and mitigation." (PMID 39301197, 2024). "Blocking a central mediator in the inflammation of gout patients (NLRP3 inflammasome) prevents cardiovascular events by activating the cytokine interleukin-1β, which affects the development of atherothrombotic plaques." (PMID 38581450, 2024).
gout (continued). "Coptisine in Huanglian can be used to treat NLRP3 inflammasome-mediated gouty arthritis by inhibiting caspase-1 to block NLRP3 inflammasome activation." (PMID 38218891, 2024). "Numerous serious human diseases, such as asthma, allergic airway inflammation, COVID-19 and gout are correlated with the overactivation of the NLRP3 inflammasome." (PMID 38720376, 2024). "Other sensors, such as NLRP3 and PYRIN, detect changes induced by DAMPs and PAMPs, with NLRP3 sensing ATP, uric acid crystals associated with gout, and various toxins." (PMID 39619229, 2024). "In view of pathogenesis, the cellular mechanism of gout is complex and it involves Toll-like receptor signaling initiation, NF-κB signaling activation, oxidative stress, and NLRP3 signaling pathway." (PMID 37637422, 2023). "Gallic acid is reported to suppress TNF-α and IL-1β levels in gouty arthritis mice model by inhibiting NLR family pyrin domain containing 3 (NLRP3) inflammasome activation." (PMID 36899361, 2023). "Overall, these findings reveal the promising effects of naturally derived compounds in inhibiting NLRP3 activation and ameliorating gout." (PMID 37598797, 2023). "Exploring the mechanism showed that BRD4 was involved in MSU induced gouty arthritis by regulating the NF‐κB/NLRP3/GSDMD signaling pathway." (PMID 37125240, 2023). "NLRP3 inflammasome activation plays an essential role in the acute inflammatory response in the context of gout." (PMID 37996809, 2023). "Functional studies further showed that USP16 was highly expressed in MSU-stimulated macrophages and induced gouty arthritis via Drp1-dependent NLRP3 inflammasome activation." (PMID 37488647, 2023). "The NLRP3 inflammasome appears to be involved in the development of several arthritic diseases, including RA, ankylosing spondylitis, and gout." (PMID 36677800, 2023). "It has also been shown that tea reduces the formation of inflammatory factors induced by urate crystals and inhibits the activation of the NLRP3 inflammatory vesicle and NF-κB pathway, thereby decreasing the likelihood of gout in patients." (PMID 38440060, 2023). "Colchicine has been shown to have several mechanisms of action in the treatment of gout, including inhibiting the activation of the NLRP3 inflammasome, blocking the release of IL-1β." (PMID 37881185, 2023). "Several NLRP3 inhibitors have been shown to alleviate gout by directly inhibiting NLRP3 inflammasome activation." (PMID 37125240, 2023). "Drp1 was elevated in MSU-induced gouty arthritis model, and it induced gouty arthritis via NF-κB pathway and NLRP3 inflammasome activation." (PMID 37488647, 2023). "Gallic acid also inhibits the production of ROS, thereby limiting the activation of NLRP3 inflammasome and pyroptosis, thereby playing a protective role in the mouse gouty arthritis model." (PMID 37125240, 2023). "Simiao decoction has been shown to alleviate gouty arthritis by inhibiting inflammation, regulating NLRP3 inflammasome, and altering gut microbiota." (PMID 37344836, 2023). "According to other evidence, GA suppressed the NLRP3 inflammasome activation in gouty arthritis of C57BL/6J mice and LPS-primed murine J774A.1 cell and bone marrow-derived macrophages." (PMID 36762118, 2023). "In the present study, the effects of different NLRP3 inflammasome activators on IL-1β secretion were evaluated in vitro using the PBMC-derived macrophages obtained from gout patients." (PMID 36686377, 2023). "Meanwhile, studies have reported increased levels of NLRP3, IL-1β and IL-18 in the serum and joint fluid of gout patients compared to healthy controls." (PMID 37954594, 2023). "More in detail, it is widely known how monosodium urate (MSU) stimulates abnormal IL-1 secretion by activating the NLRP3 inflammasome in patients with gouty arthritis." (PMID 36675455, 2023).
gout (continued). "In this context, colchicine, which is the standard of therapy for treating acute gouty arthritis, was found to inhibit the activation of the ATP-induced P2 × 7 receptor, which activates NLRP3 inflammasome by allowing potassium efflux from cytoplasm." (PMID 36675455, 2023). "In this study, we reported that Drp1 was elevated in MSU-induced gouty arthritis model, and it induced gouty arthritis via NF-κB pathway and NLRP3 inflammasome activation." (PMID 37488647, 2023). "Deubiquitinase USP16 induced gouty arthritis via Drp1-dependent mitochondrial fission and NF-κB/NLRP3 signaling." (PMID 37488647, 2023). "Although colchicine has been employed as the drug of choice for gout attack for more than 200 years, its mechanism of action was recently elucidated: suppression of the microtubule-mediated NLRP3 inflammasome." (PMID 38371945, 2023). "As predicted, gout synovial fluid served as an excellent positive control, because the inflammatory response to monosodium urate crystals leads to a NLRP3 inflammasome formation, caspase-1 activation and IL-1β release." (PMID 36936231, 2023). "Novel compounds targeting NLRP3 have also been investigated as a target to reduce inflammasome activation in gout." (PMID 37598797, 2023). "The NLRP3 inflammasome appears to play a role in the development of several arthritic diseases, including rheumatoid arthritis, ankylosing spondylitis, and gout." (PMID 36677800, 2023). "Given that NLRP3 inflammasome activation is a hallmark of AGA, we examined the levels of IL-1β, caspase-1, and NLRP3 in each group of the spontaneous gout rat model." (PMID 36686377, 2023). "Another work demonstrated that gallic acid limited the activation of NLRP3 inflammasome and Nrf2 signaling-dependent pyroptosis, and alleviated NLRP3-mediated gouty arthritis by inhibiting ROS production." (PMID 37250902, 2023). "Our NLRP3 inhibitor appears to be more efficacious in the treatment of MSU-induced gout of experimental animals than colchicine and was devoid of adverse effects on intestinal mucosa, which was observed after treatment with colchicine." (PMID 38371945, 2023). "Dietary compounds like omega-3 fatty acids can benefit inflammation-driven diseases and has potential clinical use in autoinflammatory and NLRP3-inflammasome-driven diseases, like gout." (PMID 37598797, 2023). "For example, the expression of miR-146a was significantly increased in patients with gout and involved in both NLRP3 and MyD88/NF-κB pathways." (PMID 37426193, 2023). "MSU crystal-induced acute gouty arthritis can be alleviated by autophagy induced by pP121 via inhibition of the NLRP3 inflammasome." (PMID 37881185, 2023). "Abnormal activation of NLRP3 inflammasome is related to a series of inflammatory diseases, including type 2 diabetes, gouty arthritis, non-alcoholic steatohepatitis (NASH), and neurodegenerative disorders." (PMID 37400760, 2023). "It has been suggested that autophagy induced by PP121 can alleviate MSU crystal-induced acute gouty arthritis via inhibition of the NLRP3 inflammasome." (PMID 37881185, 2023). "In contrast, costimulation with ATP sufficiently activated the NLRP3 inflammasome, leading to spontaneous gout onset in rats." (PMID 36686377, 2023). "Eucalyptol inhibits gout and joint inflammation mainly by inhibiting NLRP3 inflammasome activation and proinflammatory cytokine production through antioxidant mechanism." (PMID 37125240, 2023). "Recent studies have shown that oridonin directly binds to the NACHT domain of NLRP3 and specifically inhibits the activation of NLRP3 inflammasome, thereby alleviating gouty arthritis and type 2 diabetes in mice." (PMID 37125240, 2023). "Compelling evidence has illustrated the key roles of NLRP3 inflammasome and the pro-inflammatory cytokine IL-1β in gouty arthritis." (PMID 37488647, 2023). "In conclusion, we found that DUB USP16 induced gouty arthritis via Drp1-dependent mitochondrial fission and NF-κB/NLRP3 signaling." (PMID 37488647, 2023).
gout (continued). "MSU crystals are involved in inducing acute inflammation in gout through TLRs that stimulate the production of NLRP3 inflammasomes, interleukin-like factor and TNF-α." (PMID 38066599, 2023). "Rapid IL-1β production by activation of the NLRP3 inflammasome is the characteristic mechanism of the gout inflammatory response." (PMID 38063198, 2023). "The pathogenesis of gouty arthritis, characterized by the deposition of monosodium urate (MSU) crystals in the joints, associated to acute flares, has been associated to NLRP3 inflammasome activation and subsequent amplification of the inflammatory response." (PMID 37533852, 2023). "Our study showed that ozone inhibits TRLs signaling pathway by upregulating endogenous inflammatory brake SOCS3 to alleviate gout, which inhibit the activation of NLRP3 inflammasome at the upstream signaling pathway." (PMID 38066599, 2023). "Parallel to the localized joint gout flare, our current work revealed that circulating CMs, IMs, and DCs were highly enriched in proinflammatory factors, such as NLRP3, IL-1B, and TNF, which exhibited relatively low expression in blood NCMs and other PBMCs." (PMID 38063198, 2023). "Activation of NLRP3 inflammasome and release of IL-1β by monosodium urate crystals are pivotal pathological factors in gout attacks." (PMID 37370025, 2023). "Activation of the nod-like receptor protein 3 (NLRP3) inflammasome by monosodium urate (MSU) crystals has been identified as the molecular basis for the acute inflammatory response in gouty arthritis." (PMID 36686377, 2023). "Meanwhile, many studies have demonstrated that inhibition of NLRP3 activation can effectively alleviate gouty arthritis, but its safety and efficacy need to be further verified by more clinical trials." (PMID 38066599, 2023). "Here, our results indicated that EA remarkably decreased NLRP3 inflammasome components’ overexpression, including NLRP3, Caspase-1 and IL-1β of gout model animals." (PMID 37464384, 2023). "All of these studies demonstrate the role of the NLRP3 inflammasome and how its downstream signaling affects the development of gout and its symptoms." (PMID 37598797, 2023). "The NF-κB/NLRP3 pathway plays a central role in inflammation-related diseases, including gouty arthritis, and the blockade of the NF-κB/NLRP3 pathway is now proven to be an effective strategy to prevent and ameliorate AGA." (PMID 36824696, 2023). "In gouty arthritis mouse models, 4 reduced MSU-induced paw swelling and joint inflammation in the footpad gout model as well as neutrophil infiltration, pro-inflammatory cytokine secretion, and NLRP3 expression in MSU-triggered peritonitis." (PMID 38256888, 2023). "Oridonin, a covalent NLRP3 inhibitor, showed preventive or therapeutic effects on mouse models of gouty arthritis." (PMID 36675455, 2023). "Palmatine, tetrahydropalmatine (THP), gallic acid, and epigallocatechin gallate (EGCG), have all also been shown to attenuate MSU-crystal gouty arthritis by reducing oxidative stress-induced NLRP3 inflammasome activation." (PMID 37598797, 2023). "During the initiation phase of a gout flare, the NLRP3 inflammasome mediates the production of mature IL-1β and appears to be important." (PMID 37996809, 2023). "By targeting ASC, 8A suppressed the assembly of the NLRP3 inflammasome, thereby attenuating inflammatory diseases, including endotoxemia and gouty arthritis in mice." (PMID 36379253, 2022). "It was further revealed that miR-223-3p can directly inhibit the expression of NLRP3, thereby reducing the inflammatory effect of gout." (PMID 36339582, 2022). "The critical roles of the NLRP3 inflammasome and IL-1β in gout pathology have been revealed, and a blocking strategy for these pathways has emerged as a promising new therapeutic for gout attack." (PMID 36387275, 2022). "Among them, the nod-like receptor family pyrin domain containing 3 (NLRP3) inflammasome is involved in the development of gout as a sensor of metabolic stress." (PMID 36034697, 2022).
gout (continued). "Since IL-1β secretion is mainly mediated by activated NLRP3 inflammasome, we then examined inflammasome-dependent IL-1β secretion in culture supernatants of PBMCs from gout patients." (PMID 36052144, 2022). "With the deeper understanding of the pathological mechanism for gout, the NLRP3 inflammasome activation induced by MSU crystals is found to play a key role in gout development." (PMID 35047046, 2022). "MSU-induced gout flares are characterized by activation of the NLRP3 inflammasome which requires K+ efflux." (PMID 35368226, 2022). "The activation of the NLRP3 inflammasome and release of IL-1β are thought to be important in the progression of hyperuricemia to gout." (PMID 35464445, 2022). "In 2020, Yang and coworkers studied the NLRP3 inhibitory activity of β-carotene using gout as a disease model." (PMID 36234744, 2022). "Incorrect activation of NLRP3 inflammasome has been detected in multiple human diseases, such as type 2 diabetes, neuroinflammation, and gout." (PMID 36569930, 2022). "Because of its important function, the MAPK/NF-κB axis is a potential target for the NLRP3 inflammasome regulation during gout." (PMID 35400961, 2022). "NLRP3 participates in the progression of various inflammatory diseases, including gout and arthritis." (PMID 36052125, 2022). "Gouty arthritis is driven by macrophage uptake of deposited sodium urate crystals and subsequent activation of the NLRP3 inflammasome." (PMID 36105284, 2022). "The main mechanism by which MSU crystals cause inflammation is through activating the NLRP3 inflammasome and therefore, blocking NLRP3 or IL-1β is an effective treatment for severe or refractory gout." (PMID 36225929, 2022). "Injection of MSU crystals into this air pouch therefore recapitulates the MSU response present in the joints of gout patients and activates the NLRP3 inflammasome." (PMID 36225929, 2022). "For instance, proinflammatory cascades releasing interleukin 1β and activation of NOD-, LRR- and pyrin domain-containing protein 3 (NLRP3) inflammasomes trigger acute flares of gout." (PMID 35629321, 2022). "The production of ROS plays a vital role in NLRP3 inflammasome activation for the development of gout." (PMID 35047046, 2022). "The activation of NLRP3 inflammasome induced by monosodium urate (MSU) crystals has a critical role in gout, and its prevention is beneficial for patients." (PMID 36569930, 2022). "At the same time, NLRP3 inflammasome further aggravates alcoholic liver injury and gouty arthritis by activating plenty of macrophages." (PMID 36176434, 2022). "We also provide research information on natural extracts with NLRP3 inflammasome regulation that have been identified in animal models of MSU-induced gout within the recent 5 years." (PMID 35370689, 2022). "Recent studies have shown that MSU deposition in the joints of patients with gout can trigger the formation of NLRP3 inflammasomes." (PMID 35449811, 2022). "Studies have demonstrated that MSU crystals activate the NLRP3 inflammasome and release IL-1β to play a central role in the initiation of gout attacks." (PMID 36313318, 2022). "The data demonstrated the ability of PIP to suppress inflammation in gouty arthritis by downregulating the NLRP3 inflammasome." (PMID 35400961, 2022). "Nucleotide-binding oligomerization domain (NOD)-like receptor family pyrin domain-containing 3 (NLRP3) inflammasome-mediated IL-1β production plays a crucial role in the pathological process of gout." (PMID 35047046, 2022). "Acute gout attacks depend on the activation of macrophage TLRs/NF-κB signaling pathway (signal 1) and NLRP3 inflammasome complex/IL-1β (signal 2) dual signaling pathways." (PMID 35464862, 2022). "Various studies have been conducted on natural products that inhibit gout by targeting the NLRP3 inflammasome." (PMID 35370689, 2022). "To further elucidate the mechanism by which Z1456467176 alleviates gout inflammation, we examined the expression of the NLRP3 inflammasome pathway in rats." (PMID 36052144, 2022).